MTOR (mechanistic target of rapamycin kinase)
Diseases named in the same sentence as MTOR in open-access papers (continued):
Sharing a sentence is not in itself a finding about the gene and the disease.
tumor (continued). "Furthermore, we found that simultaneous over-expression of both miR-497 and miR-99a exhibited much stronger inhibitory effects on tumor growth than their individual effect, which is still correlated with significantly stronger repression of IGF1R and mTOR." (PMID 28624790, 2017). "Besides mTOR, HIF-1α plays a crucial role by upregulating its targets expression, BNIP3 and BNIP3L, to activate autophagy in tumor cells." (PMID 28729825, 2017). "NSC185058 has been shown to suppress tumor growth in osteosarcoma without affecting the mTOR or PtdIns3K (class III phosphatidylinositol 3-kinase) pathways." (PMID 28621712, 2017). "Despite our observation that the Ras/MEK/ERK compensatory pathway is activated in primary cells following the PI3K/AKT/mTOR inhibition, the ex vivo treatment of the PDX with a combination of KU-0063794 (mTOR inhibitor) and AZD7328 (AKT inhibitor) showed an effective reduction in tumour outgrowth." (PMID 28915623, 2017). "Indeed, recent in vitro and in vivo pre-clinical studies demonstrate efficacy with PF502 and PD901 inhibitors, which target the PI3K/mTOR and RAS/MAPK networks respectively, to achieve significant reduction in tumour burden and improvement in overall survival." (PMID 28117679, 2017). "For patient II, everolimus shrink the tumor with lower FDG in three days, which may directly result from inhibiting mTOR signal pathway." (PMID 29212287, 2017). "While PDGFr inhibition did not lead to decreased tumour growth, and mTOR alone did not decrease tumour angiogenesis, a combination of the two caused decreased pericyte coverage, decreased stromal reactivity and decreased tumour growth." (PMID 27916653, 2017). "In addition, since there are many factors that are involved in AKT/mTOR signaling pathways, it will be also important to identify what specific factors are involved in PTRF mediated tumor suppression." (PMID 27203393, 2017). "A positive or negative role for mTOR in tumor growth clearly depends on the complicated environment." (PMID 29137114, 2017). "It was found that expression levels of ERp29 in tumor specimens were negatively correlated with the PI3K/Akt/GSK3β and Akt-mTOR signaling pathway-activated gene signatures and positively correlated with the PI3K/Akt/GSK3β and Akt-mTOR signaling pathway suppressed gene signatures." (PMID 28874138, 2017). "It is now well accepted that therapeutic targeting of the PI3K/mTOR pathway alone is not sufficient for robust clinical responses in many tumour types, due to feedback loops and compensatory activation of RAS signalling." (PMID 28117679, 2017). "Finally, increased RP11-708H21.4 expression blocked AKT/mTOR pathway, and repressed in vivo CRC xenograft tumor growth." (PMID 28427191, 2017). "Tumorigenic potential of cells with activated mTOR signaling are suppressed by NOTCH inhibition, which indicate that the STAT3/p63/NOTCH axis may serve as a target for the treatment of tumor with hyperactive mTOR signaling." (PMID 28423539, 2017). "The data strongly suggest that the mTOR-mediated network in PTEN-null tumor is independent of AKT activity." (PMID 29228561, 2017). "However, by maintaining some activity against PI3Kβ, δ, γ and mTOR, SN32976 is highly effective at preventing tumor growth in preclinical tumor models." (PMID 28537878, 2017). "The results suggest that FGFR1-activated PI3K/AKT/mTOR and JAK/STAT3 signaling pathways may promote NB development and ponatinib-induced inhibition of FGFR1 signaling contributes to its anti-tumor effects." (PMID 27564113, 2017). "Apparently the synergistic inhibition of miR-497 and miR-99a on tumor growth could be interpreted by their synergistical inhibition on expression of IGF1R and mTOR." (PMID 28624790, 2017).
tumor (continued). "Another study demonstrated the enhancement of radiosensivity by using NVP-BEZ235 to block the PI3K/mTOR pathway in cisplatin-resistant NSCLC tumour cells both in vitro (reduced survival fraction after irradiation) and in vivo (increase in tumour growth delay) settings." (PMID 28320471, 2017). "The expression levels of miRNAs miR-99a, 99b, 100; 199a; 106a; 106b; 29a; 29b; 29c; 126; 200a, 200b and their respective target genes: mTOR, HIF1-α, VHL, PDGF, VEGF, VEGFR1 and VEGFR2 were analyzed using qRT-PCR in tumor tissue samples from 56 patients with ccRCC." (PMID 29202733, 2017). "In sporadic MTC without RET mutations, 69.2% of tumor samples show RAS mutations that can activate RAS/RAF/ERK and PI3K/AKT/mTOR pathways." (PMID 28476040, 2017). "Whereas phosphatidylinositol 3-kinase (PI3K)/Akt/mTOR pathway is constitutively activated in numerous kinds of tumors, suppression of PI3K/Akt survival signaling pathway due to the hypo-nutrient microenvironment leads to autophagy induction in tumor cells." (PMID 28279189, 2017). "In this study, we have shown how the method of erinacine A treatment may be used to inhibit tumour invasion of HCT‐116 cells through ROS increment and activation of the PI3K/mTOR/p70S6K signalling pathway." (PMID 27709782, 2017). "According to the molecular literature, the PI3K-AKT signaling pathway is the primary pathway for the survival of cancerous cells and is highly activated in a variety of tumor tissues; the PI3K/AKT/mTOR signaling pathway is the main regulatory pathway that negatively regulates autophagy." (PMID 28969040, 2017). "Because the PI3K/mTOR signaling pathway regulates important cellular functions, including cell proliferation, we investigated the growth-inhibitory effects of SHR8443 against a panel of human tumor cell lines." (PMID 29296217, 2017). "Immunohistochemical examination confirmed the absence of IL-6 and negligible activation of mTOR signaling in the tumor cells of non-treated mice." (PMID 28903416, 2017). "Apart from mTOR inhibitors, the negative regulator of the PI3K/Akt pathway AHRI, dual PI3K/mTOR inhibitors PI-103 and NVP-BEZ235, Akt inhibitors and the tumour suppressor gene PTEN may also be used to promote cell death in tumour cells." (PMID 28320471, 2017). "Studies carried out with animal models suggested that hyperactivation of IGF1R/mTOR signaling pathway may promote hepatocarcinogenesis, while blocking this pathway showed promising reduction of HCC tumor growth." (PMID 28624790, 2017). "In summary, these data suggest that ATR-1 exerts its anti-tumor function, at least partially, through interfere with the PI3K/AKT/mTOR signaling pathway, which may result in cellular apoptosis in the end." (PMID 26931119, 2016). "PI3K/AKT/mTOR is a crucial downstream pathway of MET and can regulate many of the biological phenomena, such as cell proliferation and survival, motility and migration, and tumor cell invasion." (PMID 27014910, 2016). "Together, in addition to its tumor suppressive activity, PP2A-B56γ3 may also participate in regulating gerosuppression by regulating levels and nuclear localization of p27 and mTOR inactivation." (PMID 26684356, 2016). "In contrast, although preclinical data have suggested PI3K pathway alterations to be predictive of anti-tumor activity in response to PI3K/Akt/mTOR inhibitors, no consensus was yet attained in early clinical trials." (PMID 27602501, 2016). "Additionally, tumor metabolism can be targeted more generally by inhibiting the growth signal pathways, such as the PI3K/AKT/mTOR and HIF-1 pathways." (PMID 26962408, 2016). "Lastly, they confirmed that PIK3R3 is a novel target gene of miR‐132 and miR‐132 might exert its tumor suppressive function by directly targeting the PIK3R3 and regulating the AKT/mTOR pathway." (PMID 27467251, 2016).
tumor (continued). "A more robust activity of novel dual PI3K/mTOR inhibitors, compared with either PI3K or mTOR inhibitors, is required for the efficient suppression of tumor growth when multiple alterations of the PI3K pathway exist, in particular in the absence of functional PTEN." (PMID 27438149, 2016). "Similarly, miR-7 and miR-320 play a tumour suppressor role by downregulating the metabolic IGF-IR/Akt and PI3K/Akt/mTOR signaling pathways." (PMID 27213336, 2016). "The MAPK/ERK and PI3K/AKT/mTOR signaling pathways may be first stimulated by the elevated expression of SHCBP1, which leads to increased tumor growth potential." (PMID 27572315, 2016). "We observed that upon withdrawal of temsirolimus treatment, there was a resumption of tumor growth in the PDX model with consequent increase in proliferative activity, decrease in apoptosis, and re-activation of mTOR pathway signaling." (PMID 27799065, 2016). "In both pT1M0 and pT1M1 tumours, a moderate-to-good positive correlation (r=0.4–0.7; Spearman's rank correlation coefficient) for HIF-1α and HIF-2α as well as co-expression of phospho-mTOR S2448 and phospho-S6RP S235/236 was found." (PMID 27291893, 2016). "We take into consideration different possible actions by n-3 PUFAs, such as the displacement of lipid raft associated onco-proteins as well as the modulation of different survival signaling pathways in tumor cells, including Wnt/β-catenin, MAPK/Erk, PI3K/Akt/mTOR, JAK-STAT and NF-κB pathways." (PMID 26821053, 2016). "Thus, simvastatin has the potential to be used as a multi-targeted agent to inhibit both PI3K/AKT/mTOR and MEK/ERK signalling and consequently suppress tumour growth." (PMID 26565813, 2016). "Therefore PI3K/AKT/mTOR (PAM) inhibitors are also suspected of indirectly inhibiting general tumor metabolism and therefore suppressing tumor acidosis." (PMID 26962408, 2016). "Indeed, blocking mTOR with sirolimus (an immunosuppressive agent widely used post LT) and first generation mTORi, has shown promising reduction of HCC tumor growth in preclinical models and in some recent clinical trials." (PMID 27577068, 2016). "PTEN is a lipid phosphatase with a canonical role in turning-off PI3K/AKT/mTOR signaling, a pathway of the RTK downstream signal (including the EGFR family), which plays important roles in regulating tumor proliferation, differentiation, migration and survival." (PMID 27029073, 2016). "Importantly, the dual PI3K and mTOR inhibitor NVPBEZ235 was previously shown to counteract the glycolytic phenotype of the BCBL1 PEL cell line and to delay tumor progression in a xenograft model of PEL." (PMID 26575168, 2016). "With this, we validated their findings despite the significantly smaller sample size of our study, stratifying patients on median (0-40% positive tumor cells) mTOR percentage as opposed to exclusively studying the minor p-mTOR-negative population (n = 9)." (PMID 27096957, 2016). "A hypoxic environment is a stimulus factor for tumor angiogenesis, and hypoxia inducing factor-1α (HIF-1α) is a key hypoxic response regulator that promotes the expression of VEGF-A, which is also a downstream component of the PI3K/Akt/mTOR signaling pathway." (PMID 26894862, 2016). "Additional experiments will be necessary to determine whether the combination of mTOR and MEK inhibitors could increase the tumor response of TNBC." (PMID 27374081, 2016). "B7-H3 expression did not alter activation of the AKT/mTOR pathway, but the high B7-H3 expression levels in the tumor cells increased cell survival and glycolysis." (PMID 26771843, 2016).
tumor (continued). "Previous reports suggested that rapamycin lacked effective activity against mTORC2 and induced feedback activation of AKT survival pathways in many tumor types, including GBM, and the activation of STAT5 by mTOR inhibition was also observed in metastatic breast cancer." (PMID 27029073, 2016). "The Ras/MAPK pathway is upstream of mTOR signaling, suggesting that ERK1/2 may modulate mTOR signaling and contribute to tumor progression." (PMID 27589685, 2016). "Clinical and preclinical evidences have suggested that resistance to sunitinib is mediated through cancer cells and tumor microenvironment plasticity to adapt to a VEGFR-independent environment by activating other survival and angiogenic pathways such as PI3K/AKT/mTOR, IL-8 or FGF-2 pathways." (PMID 27509260, 2016). "By blocking mTOR activity, DEPTOR in general should act as a tumor suppressor." (PMID 26992219, 2016). "This in turn activates RheB and mTOR/S6K1 to mediate cellular transformation and tumor formation." (PMID 27409169, 2016). "One may consider treating HER2+ tumours expressing high levels of IRS4 with drugs targeting PI3K, AKT and/or mTOR in combination with HER2-targeted therapy." (PMID 27876799, 2016). "Targeted inhibition of mTOR pathway has been studied extensively to control tumor growth and sustenance but not sufficiently understood to explore its implications to control tumor invasion and recurrence." (PMID 26940200, 2016). "To determine whether metformin treatment altered AMPK and mTOR signaling, we evaluated all four PDX tumor lines for phosphorylation of AMPK (Thr172) and p70S6K (Thr389) at the end of the 28-day treatment." (PMID 26760500, 2016). "Constitutive activation of mTOR signalling by the deletion of the Lkb1/Tsc1/Tsc2 gene in both OSE and stromal cells causes OSE hyperplasia and epithelial OvCa but no stromal tumours." (PMID 27036037, 2016). "Moreover, sublethal heat stress rapidly induces phosphoinositide 3-kinase (PI3K)/mammalian target of rapamycin (mTOR) dependent-protein kinase B (AKT) survival signaling in HCC cells in vitro and at the tumor ablation margin in vivo." (PMID 27611696, 2016). "This review will cover glucose and fatty acid metabolism, PI3K/AKT/mTOR, HIF-1 and glutamine pathways in tumor energy metabolism, and how they are being exploited for treatments and therapies by promising pre-clinical or clinical drugs being developed or investigated." (PMID 26962408, 2016). "Furthermore, a recent study reported that baicalein inhibited tumor growth in vivo via upregulation of DNA-damage-inducible transcript 4 (DDIT4) expression, which mediated the inhibition of mTOR in a breast cancer xenogeneic mouse model." (PMID 27735841, 2016). "Using established patient-derived xenograft models that successfully retain the genomic and molecular characteristics of the parental tumor, we confirmed that these anti-tumor responses occurred through the inhibition of SRC and PI3K/AKT/mTOR signaling pathways." (PMID 27438149, 2016). "Our data suggest that the PIK3/AKT/mTOR pathway is more active in left- than right-sided CRC, which provides a possible explanation for the fact that efficacy of anti-EGFR therapy differs by location of primary tumor." (PMID 27296289, 2016).
tumor (continued). "Therefore, a potential concomitant suppression of PI3K/AKT/mTOR and MAPK pathways, targeting IGF1R/IR and mTOR, can be highly detrimental for tumor growth." (PMID 26756219, 2016). "Compared to WT controls, IDO-deficient MDSCs isolated from tumor-bearing mice showed downregulated GCN2 and AMPK signaling, independent of mTOR activation." (PMID 27705910, 2016). "In vivo treatment with the dual PI3K/mTOR inhibitor LY3023414 (LY414) demonstrated a significant anti-tumor effect only in BLCAb002 and not in BLCAb001." (PMID 27823983, 2016). "Additionally, this finding reveals important mechanistic insights into tumor therapeutic resistance development and provides a platform for testing other targeted therapies on PI3K/Akt/mTOR and c-Myc axis to achieve a sustainable therapeutic outcome." (PMID 26536665, 2016). "Furthermore, upon MEK inhibition, tumours displayed a strong reduction in phosphorylated 4EBP1 levels, consistent with a role for the AKT/mTOR pathway in the response to MEK inhibition." (PMID 27922010, 2016). "We found that in tumor variants in which there is low intrinsic tumor level of PI3K/Akt/mTOR relative to that found in the stroma, blockage of pS6 activation through the use of PI3K/mTOR inhibitors interferes with MFP-induced neovascularization, immune cell infiltration and tumor regression." (PMID 26098779, 2015). "p-Akt, p-mTOR, p-S6RP and p-4EBP were detected in all tumor samples." (PMID 26502919, 2015). "Together, this study provided a preclinical proof-of-concept that combination of a PI3K/mTOR inhibitor with an AR inhibitor resulted in an anti-tumor activity in both non-CRPC and CRPC models." (PMID 26506516, 2015). "Similarly, studies have demonstrated that IGF1R and mammalian target of rapamycin (mTOR), components of IGF1R signaling pathway, are target genes of another tumor suppressor miRNA, the miR-99a." (PMID 26504785, 2015). "Together, these data are interesting, but do not convincingly provide a mechanism for mTOR inhibition induced durable MOC1 tumor control." (PMID 26506415, 2015). "The mTOR pathway regulates protein translation via eukaryotic inhibition factor 4E binding protein 1 (eIF4E-BP1) phosphorylation and the 70-kDa ribosomal protein S6 kinase (p70S6K), thereby affecting tumor cell proliferation." (PMID 26285136, 2015). "We demonstrated that this differential response is not due to enhanced tumor cell-specific effects of in vivo mTOR inhibition but rather due to preservation of antigen-specific CD8 T-cell responses that are suppressed following MEK inhibition." (PMID 26506415, 2015). "Akt/mTOR pathway was highly activated in CRPC and p-Akt was reported to target and stimulate the expression of tumorigenic factors like c-MYC, SOX2, OCT4 and eventually robust tumor growth." (PMID 26317998, 2015). "Notably, expression of Raptor, phosphorylation of mTOR and phosphorylated 4E-BP1 was also decreased in the tumor tissues from SC06-treated mice, which was consistent with the cellular studies." (PMID 26329846, 2015). "Thus, Ad- TERTp-E1A-1504 does not harm normal cells but has dual inhibiting and killing effects on TERT- and EphA3-positive tumor cells, and this effect is mediated by the AKT/mTOR signaling pathway via induction of autophagy." (PMID 25978371, 2015). "A recent work suggests that in clear RCC a cumulative number of altered biomarkers in mTOR pathway (p-AKT, p-P706SK, p-mTOR, HIF-1alfa, Raptor, PTEN, P13K, p-4EBP-1) correlates with aggressive tumour biology (tumour stage and grade) and inferior disease outcome." (PMID 26097872, 2015). "To evaluate PI3K/Akt/mTOR pathway activation in the regression of C4-HD tumors, we used the PI3K inhibitor WORT alone or in combination with MFP for 48 h, finding that WORT interfered with MFP-induced tumor reduction and tissue remodeling." (PMID 26098779, 2015). "Thus, we provided first evidence that the mTOR inhibitor, sirolimus, can efficiently suppress both allograft and xenograft FLCN-dificient tumor growth." (PMID 26418749, 2015).